ORM2 (orosomucoid 2)
Description:
Functions as a transport protein in the blood stream. Binds various hydrophobic ligands in the interior of its beta-barrel domain. Also binds synthetic drugs and influences their distribution and availability. Appears to function in modulating the activity of the immune system during the acute-phase reaction.
Synonyms: AGP2; AGP-B; AGP-B'
Tractability: Small molecule: a structure with a bound ligand is known; it has a high-quality binding pocket. Antibody: its Gene Ontology location is reachable by antibodies, with high confidence; UniProt places it where antibodies can reach, with medium confidence; UniProt predicts a signal peptide or a membrane-spanning region.
Target class: Secreted protein
Gene: Protein-coding gene on chromosome 9 (114,329,788 to 114,333,254, forward strand). Ensembl gene ENSG00000228278.
Subcellular location: Secreted
Subcellular location (Human Protein Atlas): Vesicles; Golgi apparatus; Predicted to be secreted
Pathways (Reactome):
Hemostasis: Platelet degranulation
Immune System: Neutrophil degranulation
Gene Ontology:
Molecular function: protein binding; molecular carrier activity
Biological process: positive regulation of interleukin-1 beta production; positive regulation of interleukin-1 production; positive regulation of tumor necrosis factor production; acute inflammatory response to antigenic stimulus; acute-phase response; regulation of immune system process
Cellular component: blood microparticle; extracellular exosome; extracellular region; azurophil granule lumen; platelet alpha granule lumen; specific granule lumen
Genetic constraint (gnomAD): Loss-of-function variants: 18 observed, 25.13 expected, observed/expected ratio (o/e) 0.72, 90% interval 0.49 to 1.06. The upper end of that interval is the gene's LOEUF score, 1.06, which puts it in group 4 of 6, group 1 being the genes least tolerant of losing a copy. Missense variants: 226 observed, 193.98 expected, observed/expected ratio (o/e) 1.17, 90% interval 1.04 to 1.3. Synonymous variants: 83 observed, 72.71 expected, observed/expected ratio (o/e) 1.14, 90% interval 0.95 to 1.37.
Homologues: Orthologues: chimpanzee ORM2 (98% identical), rabbit ORM1 (60% identical), mouse Orm1 (48% identical), rat Orm1 (48% identical), mouse Orm3 (44% identical), mouse Orm2 (43% identical), zebrafish apom (16% identical). Paralogues in human: ORM1 (90% identical).
Diseases named in the same sentence as ORM2 in open-access papers:
ORM2 is named in the same sentence as 63 diseases in open-access papers, as found by Europe PMC text mining. Sharing a sentence is not in itself a finding about the gene and the disease. The quoted sentences say what the papers report.
COVID-19 (8 papers, 2022 to 2025). A disease caused by infection with severe acute respiratory syndrome coronavirus 2. "Many of these proteins, such as SERPINA3, ORM1 and ORM2, have been used to distinguish between mild and severe cases of COVID-19." (PMID 38965561, 2024). "The COVID-19 convalescents had significantly elevated immunoglobulins, Orosomucoid 2 (ORM2), peroxiredoxin-2 (PRDX2), hemoglobin subunits (HBD, HBB and HBA1), as well as proteins involved in cholesterol transport such as cholesteryl ester transfer protein (CETP) and apolipoprotein A1 (APOA1)." (PMID 38396092, 2024). "In line with the cytokine storm hypothesis, several acute phase proteins were elevated in serum of COVID-19 patients, such as CRP, Lipopolysaccharide Binding Protein (LBP), ORM1, and ORM2." (PMID 37739942, 2023). "Cluster 12 and 13 report proteins that are increased in all COVID-19 patients but at higher levels in ICU/F patients which are mainly constituted by proteins playing a role in acute inflammatory response (CRP, ORM1, ORM2, SAA1, SAA2, S100A8, S100A9, Serpin A3)." (PMID 36348270, 2022).
rheumatoid arthritis (6 papers, 2018 to 2025). A chronic, systemic autoimmune disorder characterized by inflammation in the synovial membranes and articular surfaces. "This research aimed to explore the function of Orosomucoid-2, a protein produced during the body’s initial response to injury, in rheumatoid arthritis, a chronic inflammatory disorder." (PMID 38556552, 2024). "There was a positive correlation between the levels of ORM2 and disease activity of rheumatoid arthritis, which was a common inflammatory diseases." (PMID 34035220, 2021). "ORM2 was founded to be associated with microglial interaction, SAA4 was identified as a rheumatoid arthritis-screening biomarker, and MAP2K6 was reported to be involved in the pathogenesis of colorectal adenocarcinoma." (PMID 32130204, 2020). "Additionally, it is known that glycosylation patterns of orosomucoid 2 are distinct among inflammatory and autoimmune diseases (e.g., rheumatoid arthritis, SLE, autoimmune thyroiditis, etc.), thereby, affecting their physical properties and function." (PMID 29323127, 2018). "In the present study, global proteome profiling of serum and urine revealed that orosomucoid-2 (ORM2), an acute phase reactant, was differentially expressed in rheumatoid arthritis (RA) patients and exhibited the highest fold change." (PMID 38556552, 2024). "Here, global proteome profiling of serum and urine revealed that orosomucoid-2 (ORM2), an acute phase reactant, was differentially expressed in rheumatoid arthritis (RA) patients and showed the highest fold change." (PMID 38556552, 2024).
Sepsis (4 papers, 2020 to 2024). Sepsis is defined as life-threatening organ dysfunction caused by a dysregulated host response to infection. "Genes encoding members of the acute phase protein response, C-reactive protein (Crp), and orosomucoid 1 and 2 (Orm1, Orm2) belong to the group of genes upregulated by sepsis in both organs." (PMID 37638006, 2023). "ORM2 interacts with TLR2 signaling involved in the pathobiology of sepsis." (PMID 32174955, 2020).
atherosclerosis (3 papers, 2014 to 2025). A disease characterized by the build-up of fatty material and calcium deposition in the arterial wall resulting in partial or complete occlusion of the arterial lumen. "Exogenous administration of recombinant ORM2 or long-acting ORM2-IgG Fc has been shown to attenuate hepatic steatosis, steatohepatitis, hyperlipidemia, and atherosclerosis in preclinical mouse models." (PMID 40243151, 2025). "Three cardiovascular signaling pathways identified by IPA software including “Atherosclerosis Signaling” (related gene: ORM1, ORM2, and S100A8)." (PMID 36277748, 2022). "In addition to cytokine and chemokines genes the “Atherosclerosis Signalling” and “Communication between Innate and Adaptive Immune cells” pathways had CD40, ICAM1, ORM1 and ORM2 as being significantly expressed within the pathways at 1 hour following LPS and Pam3CSK4 stimulation." (PMID 24842522, 2014).
ovarian cancer (3 papers, 2010 to 2023). A primary or metastatic malignant neoplasm involving the ovary. "In addition, five new proteins with increased expression in ovarian cancer sera were identified: alpha-1-antitrypsin (AAT), apolipoprotein E (APOE), extracellular matrix protein-1 (ECM1), inter-alpha globulin inhibitor-H3, orosomucoid-2 (ORM2)." (PMID 20546617, 2010).
Arthritis (2 papers, 2020 to 2024). Inflammation of a joint. "First, we observed ORM2-induced exacerbation of IL-1β-induced arthritis over a relatively short period of 7 days." (PMID 38556552, 2024). "After inducing IL-1β-induced arthritis in mice, the Orm2 mRNA expression level increased up to 65.3-fold and 3.2-fold in the liver and affected joints, respectively, as determined by qPCR." (PMID 38556552, 2024). "We demonstrated that an intra-articular injection of recombinant ORM2 into affected joints aggravated the severity of IL-1β-induced arthritis in mice, accompanied by a marked increase in macrophage infiltration." (PMID 38556552, 2024). "Intra-articular injection of ORM2 increased the severity of arthritis in mice and accelerated the infiltration of macrophages into the affected joints." (PMID 38556552, 2024). "Considering that ORM2 was synthesized at markedly greater levels in the liver than in the affected joints of mice with IL-1β-induced arthritis, a local form of chronic arthritis, we suspect that liver-derived ORM2 could also participate in this process." (PMID 38556552, 2024). "Moreover, compared with vehicle injection, intra-articular injection of ORM2 markedly exacerbated the suboptimal severity of IL-1β-induced arthritis, as assessed by inflammatory cell infiltration and synovial hyperplasia." (PMID 38556552, 2024). "In mice, ORM2 was found to worsen arthritis and increase the presence of macrophages." (PMID 38556552, 2024). "Therefore, whether urinary ORM2 could be a predictive biomarker for arthritis in AOSD is a meaningful topic and requires a long-term follow-up study." (PMID 33013889, 2020).
autoimmune disease (2 papers, 2018 to 2025). A disorder resulting from loss of function or tissue destruction of an organ or multiple organs, arising from humoral or cellular immune responses of the individual to their own tissue constituents. "Binders that block ORM2-mediated immune signaling could serve as potential anti-inflammatory agents or probes to dissect its role in autoimmune disease." (PMID 41394589, 2025).
depression (2 papers, 2023 to 2024). "Additionally, there exist a multitude of significant genes that vary between sexes and are linked to depression, like ORM1, ORM2, RNF32, SLC25A5, Thbs1, and Cadps2 etc., manifesting sex-specific impacts on depression risk." (PMID 38903903, 2024).
Hepatic steatosis (2 papers, 2025). Steatosis is a term used to denote lipid accumulation within hepatocytes. "This study examined the association between circulating ORM2 levels and the severity of hepatic steatosis, insulin resistance, and T2DM in a cohort of 449 adults." (PMID 40943248, 2025). "In vivo studies demonstrated that ORM2 deficiency exacerbates HFD-induced hepatic steatosis and high-fat high-cholesterol (HFHC) diet-induced steatohepatitis in mice." (PMID 40243151, 2025). "Moreover, logistic regression analyses underscored ORM2 as an independent predictor of severe hepatic steatosis, with each unit increase in ORM2 associated with 0.5% greater odds of severe steatosis (AOR = 1.005; 95% CI: 1.002–1.007, p < 0.001)." (PMID 40943248, 2025). "On the other hand, the current study revealed that elevated ORM2 levels were significantly correlated with greater hepatic steatosis, insulin resistance, triglycerides, ALT, and hip circumference." (PMID 40943248, 2025). "In conclusion, this study establishes circulating ORM2 as a significant and independent predictor of hepatic steatosis severity and metabolic dysfunction." (PMID 40943248, 2025). "The principal finding of this study was that elevated ORM2 levels significantly correlated with increased severity of metabolic dysfunction, specifically hepatic steatosis, insulin resistance, and levels of TG and ALT." (PMID 40943248, 2025). "Conversely, ORM2 overexpression mitigates hepatic steatosis and steatohepatitis and improves plasma lipid profiles." (PMID 40243151, 2025). "Statistical analyses using Spearman correlation and multiple logistic regression revealed that elevated ORM2 levels were significantly correlated with greater hepatic steatosis, insulin resistance, triglycerides, ALT, and hip circumference (p < 0.001)." (PMID 40943248, 2025). "MAFLD was assessed using FibroScan® with hepatic steatosis categorized by Controlled Attenuation Parameter (CAP) scores, while plasma ORM2 levels were measured via ELISA." (PMID 40943248, 2025).
Insulin resistance (2 papers, 2020 to 2025). Increased resistance towards insulin, that is, diminished effectiveness of insulin in reducing blood glucose levels. "The association of ORM2 with insulin resistance in T2DM was earlier reported." (PMID 33184417, 2020). "This study aims to investigate the association between ORM2, MAFLD, T2DM, and insulin resistance in individuals from the Kuwait Adult Diabetes and Epidemiological Multidisciplinary (KADEM) program." (PMID 40943248, 2025). "With strong performance in ROC analysis and robust associations with insulin resistance and liver enzyme levels, ORM2 holds promise as a non-invasive diagnosis for MAFLD, involving only blood sampling without direct invasion of the liver." (PMID 40943248, 2025).
ischemic stroke (2 papers, 2020 to 2024). A stroke disorder caused by obstruction of blood flow to the brain, due to thrombotic (local blood clot formation) or embolic (due to a blood clot or other material traveling from another site) event. "Past studies have described the role of ORM2 in neuroinflammation and ischemic stroke events, and the existence of astrocyte-produced ORM2 was also deciphered." (PMID 38719902, 2024). "Past investigations have delineated the role of ORM2 in neuroinflammation and ischemic stroke events." (PMID 38719902, 2024). "Thus, our present findings, in conjunction with the mouse Orm2 study, suggest that the high upregulation of Orm2 would protect Cbs−/− mice from ischemic stroke, and that this protective response is not induced in CBS−/− patients." (PMID 32612202, 2020).
liver cancer (2 papers, 2022 to 2023). An epithelial or non-epithelial malignant neoplasm that arises from the liver. "CMTM7 and ORM2 as IRGs, CMTM7 acts as a tumor suppressor by inhibiting cell cycle progression in liver cancer, and ORM2 is closely associated with cancer-promoting pathways for liver cancer." (PMID 36353638, 2022).
liver diseases (2 papers, 2022 to 2024). "Additionally, ORM2 has shown promise as a biomarker for liver diseases, contributing to diagnostics and monitoring, emphasizing its significance in liver health and potential for therapeutic interventions." (PMID 38719902, 2024).
liver fibrosis (2 papers, 2022 to 2025). "Although we noticed an upregulation of select acute phase response (e.g., Saa1, Saa2, and Orm2) and fibrosis genes (e.g., Col1a1 and Timp1) in livers of IXA4-treated DIO mice, IXA4 treatment did not increase liver fibrosis or the levels of multiple plasma cytokines." (PMID 35105890, 2022).
melanoma (2 papers, 2021 to 2023). A malignant, usually aggressive tumor composed of atypical, neoplastic melanocytes. "Eleven genes were significantly differentially expressed between metastases and primary tumors, and ALB, ORM2, CRABP1, and APOH may be associated with the metastasis of melanoma." (PMID 34154655, 2021). "There is no relevant functional study on the relationship between ALB, ORM2, CRABP1, and APOH and melanoma metastasis, which may represent future candidates." (PMID 34154655, 2021).
non-alcoholic steatohepatitis (2 papers, 2022 to 2024). "A recent study identified orosomucoid 2 (ORM2) as a key regulatory protein in de novo lipogenesis in non-alcoholic steatohepatitis and showed preclinical data on beneficial pharmacological targeting." (PMID 39317442, 2024).
Stroke (2 papers, 2010 to 2020). Sudden impairment of blood flow to a part of the brain due to occlusion or rupture of an artery to the brain. "Because of its effects on inflammation, ORM2 has been suggested to have a protective effect on stroke in humans." (PMID 32612202, 2020).
acute liver failure (1 paper, 2024). Rapid deterioration of liver function causing encephalopathy and coagulopathy. "ORM2 has been implicated in autoimmune and infectious diseases, including adult-onset Still’s disease, hepatitis B virus-induced acute liver failure, and tuberculosis." (PMID 38556552, 2024).
acute myocardial infarction (1 paper, 2018). Necrosis of the myocardium, as a result of interruption of the blood supply to the area. "Alpha-1-acid glycoprotein 2, also known as orosomucoid-2, has been found at increased levels in patients with acute myocardial infarction and has anti-inflammatory properties." (PMID 30594242, 2018).
adenoma (1 paper, 2012). A neoplasm arising from the epithelium. "Plasma ORM2 levels on a log scale in box-and-whisker plots, median plasma ORM2 concentrations were significantly higher in CRC compared to the normal colorectum, hyperplastic polyp, and adenoma (all at P<0.001, respectively)." (PMID 22363757, 2012). "It was found that ORM2 were significantly increased in patients suffering from CRC and IBD compared with normal individuals and patients with hyperplastic polyp and adenoma." (PMID 22363757, 2012). "Plasma ORM2 concentrations were significantly higher in CRC compared to the normal colorectum, hyperplastic polyp, and adenoma (P<0.001)." (PMID 22363757, 2012). "The plasma ORM2 level was statistically significantly higher in patients with IBD than in the normal colorectum, colorectal hyperplastic polyp and adenoma (all at P<0.001, respectively) and it was statistically significantly higher in patients with IBD than in CRC (P<0.05)." (PMID 22363757, 2012).
breast carcinoma (1 paper, 2010). "The level of ORM2 determined by Western blot increased by 2.05 fold in the pooled plasma of breast cancer, whereas the ICAT ratio was 1.85 relative to that of normal healthy control." (PMID 20346108, 2010). "Among the four biomarker candidates, ORM2 showed significant up-regulation in both biopsied and LCM breast cancer tissues relative to normal controls (p < 0.001), whose log2-transformed fold changes (log2FC) in the medians were 0.88 and 1.09, respectively." (PMID 20346108, 2010).
cerebral malaria (1 paper, 2013). A sequestration of Plasmodium falciparum in the brain, which can cause coma and/or seizures. "An increase in orosomucoid 2, differentially expressed in both plasma and CSF of patients with cerebral malaria, together with an increased production of ceruloplasmin and glutathione, would enhance antioxidant defenses and limit the stimulatory effects of oxidant molecules on cytokine production." (PMID 23888081, 2013).
chronic pancreatitis (1 paper, 2025). A chronic inflammatory process causing damage and fibrosis of the pancreatic parenchyma. "For instance, AZGP1 and ALB were highlighted as potential diagnostic markers in chronic pancreatitis while ORM2 has been implicated in inflammatory pancreatic conditions." (PMID 41007761, 2025).
gastric cancer (1 paper, 2015). A primary or metastatic malignant neoplasm involving the stomach. "Moreover, other proteins revealed in both reports included upregulated A2GL (LRG1), ITIH3, ORM2 and SHGB, which collectively indicated very high conformity of serum proteome signature of gastric cancer that based on samples of unrelated Polish and India’s populations." (PMID 26376850, 2015).
hepatocellular carcinoma (1 paper, 2015). A malignant tumor that arises from hepatocytes. "However, little is known regarding the function of ORM2 in hepatocellular carcinoma (HCC)." (PMID 25965830, 2015).
injury (1 paper, 2026). Damage inflicted on the body as the direct or indirect result of an external force, with or without disruption of structural continuity. "Knock out Orm2 exacerbates liver damage, while its overexpression provides protection, identifying ORM2 as an endogenous hepatoprotective factor during acute liver injury." (PMID 42062254, 2026).
ischemia (1 paper, 2026). A hypoperfusion of the BLOOD through an organ or tissue caused by a PATHOLOGIC CONSTRICTION or obstruction of its BLOOD VESSELS, or an absence of BLOOD CIRCULATION. "Exogenous administration of ORM2 effectively ameliorates ferroptosis and tissue damage in multiple ischemia-reperfusion injury models." (PMID 42062254, 2026).
leukemia (1 paper, 2018). A malignant (clonal) hematologic disorder, involving hematopoietic stem cells and characterized by the presence of primitive or atypical myeloid or lymphoid cells in the bone marrow and the blood. "For instance, ORM1 and ORM2 are already shown to be involved in AML, LTF is a high-profile gene whose role in AML needs further investigation, and S100A12 is shown to be involved in similar subtypes of leukemia, such as ALL, and is suggested to be involved in AML as well." (PMID 29589558, 2018).